PHF21A (PHD finger protein 21A)
Description:
Component of the BHC complex, a corepressor complex that represses transcription of neuron-specific genes in non-neuronal cells. The BHC complex is recruited at RE1/NRSE sites by REST and acts by deacetylating and demethylating specific sites on histones, thereby acting as a chromatin modifier. In the BHC complex, it may act as a scaffold. Inhibits KDM1A-mediated demethylation of 'Lys-4' of histone H3 in vitro, suggesting a role in demethylation regulation.
Synonyms: BHC80; KIAA1696; BM-006; IDDBCS; NEDMS
Tractability: PROTAC: UniProt records ubiquitination sites on it; ubiquitination databases record sites on it; its protein half-life has been measured.
Gene: Protein-coding gene on chromosome 11 (45,929,319 to 46,121,473, reverse strand). Ensembl gene ENSG00000135365.
Subcellular location: Nucleus
Subcellular location (Human Protein Atlas): Nucleoplasm
Pathways (Reactome):
Chromatin organization: HDACs deacetylate histones
Disease: Potential therapeutics for SARS
Hemostasis: Factors involved in megakaryocyte development and platelet production
Gene Ontology:
Molecular function: protein binding; chromatin binding
Cellular component: DNA repair complex; histone deacetylase complex; nucleoplasm; nucleus
Genetic constraint (gnomAD): Loss-of-function variants: 3 observed, 52.07 expected, observed/expected ratio (o/e) 0.0576, 90% interval 0.025 to 0.15. The upper end of that interval is the gene's LOEUF score, 0.15, which puts it in group 1 of 6, group 1 being the genes least tolerant of losing a copy. Missense variants: 452 observed, 675.07 expected, observed/expected ratio (o/e) 0.67, 90% interval 0.62 to 0.72. Synonymous variants: 232 observed, 252.99 expected, observed/expected ratio (o/e) 0.92, 90% interval 0.82 to 1.02.
Gene-disease validity (ClinGen):
ClinGen rates the evidence that PHF21A causes each of these diseases.
complex neurodevelopmental disorder (autosomal dominant): Definitive. A disorder that involves more than one phenotype associated with the central nervous system, including but not limited to intellectual disability, autism, and seizures (epilepsy).
Homologues: Orthologues: chimpanzee PHF21A (99% identical), macaque PHF21A (99% identical), dog PHF21A (99% identical), guinea pig PHF21A (98% identical), pig PHF21A (98% identical), rat Phf21a (97% identical), rabbit PHF21A (97% identical), mouse Phf21a (95% identical), tropical clawed frog phf21a (80% identical), zebrafish phf21ab (62% identical), zebrafish phf21aa (33% identical). Paralogues in human: PHF21B (28% identical), ZMYND8 (14% identical), PHF12 (12% identical), AIRE (12% identical), ZMYND11 (7% identical).
Diseases named in the same sentence as PHF21A in open-access papers:
PHF21A is named in the same sentence as 30 diseases in open-access papers, as found by Europe PMC text mining. Sharing a sentence is not in itself a finding about the gene and the disease. The quoted sentences say what the papers report.
Intellectual disability (9 papers, 2013 to 2024). "PHF21A has been associated with intellectual disability and craniofacial anomalies based on its deletion in the Potocki-Shaffer syndrome region at 11p11.2 and its disruption in three patients with balanced translocations." (PMID 31649809, 2019). "This suggests that PHF21A is involved in autism spectrum disorder and intellectual disability, and its haploinsufficiency causes a diverse neurological phenotype." (PMID 31649809, 2019). "These include PHF21A/BHC80, a PHD finger containing-chromatin reader whose mutation causes intellectual disabilities and craniofacial dysmorphisms including microcephalies." (PMID 38992439, 2024). "Disruption of the PHF21A gene triggers syndromic intellectual disability with craniofacial anomalies, and neurobehavioral problems including autism." (PMID 36992502, 2023). "Clinical cardinal features of PSS syndrome are multiple exostoses (due to the EXT2 involvement), biparietal foramina (due to the ALX4 involvement), intellectual disability, and craniofacial anomalies (due to the PHF21A involvement)." (PMID 36555772, 2022). "Current literature implies a minimal region with haploinsufficiency of three genes, ALX4 (parietal foramina), EXT2 (multiple exostoses), and PHF21A (craniofacial anomalies, and intellectual disability)." (PMID 33126574, 2020). "Patients with a deletion involving ALX4, ELX2, and PHF21A genes had the cardinal PSS features: biparietal foramina, multiple exostosis, and intellectual disability and craniofacial anomalies associated with ALX4, ELX2, and PHF21A, respectively." (PMID 33126574, 2020). "PHF21A is a member of the BRAF35/histone deacetylase complex that mediates repression of neuron-specific genes and has previously been associated with ASD and intellectual disability." (PMID 36117209, 2023). "Since PHF21A strongly correlates with intellectual disability, we suggest that it could also be the leading gene for the infantile spasms and epilepsy." (PMID 33126574, 2020). "Disruption of PHF21A has previously been implicated in the causation of intellectual disability (but not aniridia)." (PMID 27124303, 2016).
Potocki-Shaffer syndrome (5 papers, 2017 to 2022). Potocki-Shaffer syndrome is characterized by multiple exostoses, parietal foramina, enlargement of the anterior fontanelle and occasionally intellectual deficit and mild cranio-facial anomalies. "Loss of PHF21A is associated with Potocki-Shaffer Syndrome (PSS) in humans and is associated with craniofacial and neurological complications." (PMID 33954026, 2021). "Data from literature relates PHF21A variants with Potocki-Shaffer Syndrome (PSS), a contiguous gene deletion disorder caused by the haploinsufficiency of PHF21A, ALX4, and EXT2 genes." (PMID 36555772, 2022). "PHF21A was translocated in patients with Potocki-Shaffer syndrome (PSS; OMIM 601224), characterized by multiple exostoses, parietal foramina, intellectual disability, and craniofacial anomalies." (PMID 28665350, 2017).
autism (4 papers, 2019 to 2024). Persistent deficits in social interaction and communication and interaction as well as a markedly restricted repertoire of activity and interest as well as repetitive patterns of behavior. "When we expanded the dataset to include the entire 271 autism susceptibility genes that are expressed in the human amygdala, we found an additional five genes (PHF21A, RNABP17, ELP4, CNKSR2, and NAV2) with altered expression in individuals with ASD." (PMID 32460837, 2020). "Notably, many autism-associated DEGs, such as Zbtb20 and Phf21a, exhibited pronounced dysregulation in deep layer excitatory neurons." (PMID 39604385, 2024).
epilepsy (4 papers, 2019 to 2022). A brain disorder characterized by episodes of abnormally increased neuronal discharge resulting in transient episodes of sensory or motor neurological dysfunction, or psychic dysfunction. "Intellectual disability and epilepsy in human patients were found to be caused by de novo truncating variants in PHF21A." (PMID 35866480, 2022). "Our results extend the phenotypic spectrum of PHF21A mutations by adding autism spectrum disorder, epilepsy, hypotonia, and neurobehavioral problems." (PMID 31649809, 2019). "Notably, PHF21A disruption has also been associated with hypotonia, and different types of epilepsy among which West-like epileptic encephalopathy." (PMID 33126574, 2020). "Additionally, some of our patients display ASD, epilepsy, ADHD, anxiety disorder, hypotonia, tapering fingers, clinodactyly, and syndactyly, which extends the clinical features caused by PHF21A mutations." (PMID 31649809, 2019). "The authors have concluded that PHF21A haploinsufficiency results in ID and craniofacial anomalies, and possibly contributes to ASD, epilepsy, and overgrowth." (PMID 31649809, 2019). "The profound expression in the human fetal brain emphasizes the role of PHF21A in early human development, which is consistent with features in our patients, such as developmental delay, ASD, ADHD, and epilepsy observed at an early age." (PMID 31649809, 2019).
glioma (4 papers, 2017 to 2022). A benign or malignant brain and spinal cord tumor that arises from glial cells (astrocytes, oligodendrocytes, ependymal cells). "Kaplan–Meier analyses of GSE4412 and GSE4271 datasets demonstrated that downregulation of PHF21A was closely associated with a decreased OS rate among patients with glioma." (PMID 35270630, 2022). "In the signature, HDAC1 (HR:1.4938) and RBL1 (HR:1.7148) were deemed a hazard, while RUNX1T1 (HR:0.7349), FKBP3 (HR:0.6382), and PHF21A (HR:0.4956) promoted survival possibilities for glioma patients." (PMID 34540896, 2021). "According to the analysis, we found that only the downregulation of CDK17, GNA13, PHF21A, and MTHFD2 was closely associated with a decreased overall survival among patients with glioma." (PMID 29362722, 2017). "Survival analysis found that CDK17, GNA13, PHF21A, and MTHFD2 are closely associated with glioma." (PMID 29362722, 2017). "HDAC-related genes upregulated in IDH1/2mut glioma include HDAC2/4/5, KDM1A, CHD4, MTA2/3, SIRT1/2, PHF21A, and BRMS1L." (PMID 34424450, 2021). "Up to now, the biological functions of CDK17, GNA13, PHF21A, and MTHFD2 in glioma have remained unclear." (PMID 29362722, 2017). "According to the study, downregulation of CDK17, GNA13, PHF21A, and MTHFD2 can be considered as biomarkers or therapeutic targets for glioma." (PMID 29362722, 2017). "The results suggested that CDK17, GNA13, PHF21A, and MTHFD2 might play important roles and potentially be valuable in the prognosis and treatment of glioma." (PMID 29362722, 2017).
cognitive deficits (1 paper, 2024). "Second, loss-of-function mutations in both genes, KDM1A and PHF21A, cause rare neurodevelopmental disorders that involve cognitive deficits." (PMID 39395799, 2024). "Since these mutations impact both canonical and neuronal isoforms of LSD1 and PHF21A, it remains to be determined which isoform is responsible for observed cognitive deficits." (PMID 39395799, 2024).
colorectal cancer (1 paper, 2025). A primary or metastatic malignant neoplasm that affects the colon or rectum. "For instance, PHF21A, over-expressed in our study, is implicated in colorectal cancer, enhancing lymphangiogenesis and immune cell infiltration associated with metastasis." (PMID 39941055, 2025).
Epileptic spasm (1 paper, 2020). A sudden flexion, extension, or mixed extension-flexion of predominantly proximal and truncal muscles that is usually more sustained than a myoclonic movement but not as sustained as a tonic seizure. "We suggest PSS cases may have epileptic spasms early in life, and PHF21A is likely to be the causative gene." (PMID 33126574, 2020).
Gillespie syndrome (1 paper, 2016). "It seems reasonable to consider individual 1371 as having a composite phenotype with PHF21A-disrupting breakpoint exacerbating the neurodevelopmental problems but the Gillespie syndrome being, as yet, unexplained." (PMID 27124303, 2016). "Direct sequencing of the coding exons and essential splice sites of PHF21A and ARHGAP6 revealed only polymorphic variants in the 10 individuals with Gillespie syndrome who lacked a detectable chromosomal abnormality at these loci." (PMID 27124303, 2016).
hepatocellular carcinoma (1 paper, 2024). A malignant tumor that arises from hepatocytes. "It has been found that PHF21A serves as a biomarker for the progression and prognosis of hepatocellular carcinoma (HCC)." (PMID 38167072, 2024).
infantile spasms (1 paper, 2020). A rare epilepsy syndrome characterized by onset of epileptic spasms in infants between 2 and 12 months of age, and rarely up to 24 months. "On the other hand, we found two neonates, while searching infantile spasms among cases with PHF21A point mutations (one truncating and one missense variant)." (PMID 33126574, 2020).
iron deficiency (1 paper, 2023). "To date, no relevant studies have reported the mechanism of PHF21A involvement in iron deficiency and PCOS." (PMID 36873892, 2023).
lung carcinoma (1 paper, 2022).
Obesity (1 paper, 2019). Accumulation of substantial excess body fat. "Intriguingly, obesity may be another feature caused by PHF21A mutation, seen in three of our patients (patients 1, 3, and 5), as well as in a female with a balanced translocation and PHF21A truncation." (PMID 31649809, 2019).
neurodevelopmental disorder (5 papers, 2019 to 2025). A behavioral and cognitive disorder with onset during the developmental period that involves impaired or aberrant development of intellectual, motor, or social functions. "Also, we have identified 15 de novo variants in genes that were previously implicated in ASD or related neurodevelopmental disorders (PHF21A, WASF1, TCF20, DEAF1, MED13, CREBBP, KDM6B,SMURF1, ADNP, CACNA1G, MYT1L, KIF13B, GRIA2, CHM, and KCNK9)." (PMID 38572415, 2024). "PHF21A, also known as BHC80, is the molecule that recognizes unmethylated H3K4, and essential for neuronal and craniofacial development, and PHF21A loss of function may result in dysregulation of histone methylation and drive neurodevelopmental disorders 67,68." (PMID 31523167, 2019). "PHD finger protein 21A (PHF21A) was mainly studied in neurodevelopmental disorders." (PMID 34540896, 2021).
tumor (5 papers, 2016 to 2025). "NUMBL and PHF21A were upregulated but PDGFRA was downregulated in tumor samples compared with normal samples in the Human Protein Atlas (HPA) database." (PMID 38167072, 2024). "In tumor tissue, the averaged fold-change (tumor tissue compared to normal lung parenchyma) ranged from 0.92 (PHF21A) to 8.7 (CTGF)." (PMID 29467960, 2018). "PHF21A, involved in histone deacetylation, affects gene expression, cellular stress responses, and can contribute to neuroinflammation, impaired memory, and tumor formation." (PMID 39941055, 2025). "We also demonstrated that high expression of NUMBL and PHF21A, but low expression of PDGFRA in tumor tissues compared with normal tissues." (PMID 38167072, 2024). "Averaged normalized gene expression levels in tumor tissue ranged from 0.03 (PHF21A–PHD Finger Protein 21A) to 161.0 (CTGF) and in blood from 0.01 (PHF21A) to 329.0 (CTGF)." (PMID 29467960, 2018). "Among them, we selected five decreased (CCDC28B, SREK1IP1/P18SRP/SFRS12IP1, RASL10B, PHF21A/BHC80 and PGC) and two increased genes (IL-11 and CXCL2), by microarray, as differentiation-, splicing-, inflammation-, or tumor-related genes." (PMID 26701885, 2016).
adenocarcinoma (1 paper, 2020). A common cancer characterized by the presence of malignant glandular cells. "Interestingly, another member of REST transcriptional repressor complex, PHD finger protein 21A (PHF21A) is differentially spliced in NEPC cases compared to adenocarcinoma." (PMID 32754615, 2020).
PHF21A also shares sentences with these, for which no sentence is quoted: aniridia (1 paper); anxiety disorder (1); Ataxia (1); autism spectrum disorder (1); cancer (1); conotruncal heart defects (1); developmental delay (1); diabetic retinopathy (1); Epileptic encephalopathy (1); microcephaly (1); Neurodevelopmental delay (1); pancreatic cancer (1); speech disorder (1).